FNDC4 (fibronectin type III domain containing 4)
Diseases named in the same sentence as FNDC4 in open-access papers (continued):
Sharing a sentence is not in itself a finding about the gene and the disease.
breast carcinoma (2 papers, 2022 to 2023). "In addition, only 1 significant prognostic analysis of FNDC4 was found in the 4 intrinsic subtypes of breast cancer." (PMID 36626432, 2022). "In contrast, higher FNDC3A, FNDC4, and FNDC5 predicted better survival for breast cancer patients." (PMID 36626432, 2022). "FNDC4 and FNDC6 are relevant to survival curves in colorectal and breast cancer." (PMID 36626432, 2022).
COVID-19 (2 papers, 2024 to 2025). A disease caused by infection with severe acute respiratory syndrome coronavirus 2. "Their research suggests that FNDC4 may lead to a better prognosis in obese patients with COVID-19." (PMID 39325938, 2024). "RETREG1, along with FNDC4, also inhibits SARS-CoV-2 viral replication, suggesting that components of the ERAD pathway may serve as inhibitors of COVID-19 BIs." (PMID 40650217, 2025).
diabetes (2 papers, 2021 to 2024). "The liver mainly controls the circulating level of sFNDC4, and the reduction of liver factor FNDC4 leads to pre-diabetes in mice, that’s because sFNDC4 promoted insulin signal transduction and insulin mediated glucose uptake in white adipocytes." (PMID 39325938, 2024). "Overall, these findings demonstrate that decreasing liver and circulating FNDC4 promoted a state of pre-diabetes, manifested by glucose intolerance combined with compensatory hyperinsulinemia and subsequent hyperglycemia." (PMID 34016966, 2021). "Thus, GPR116Ad−/− mice showed signs of pre-diabetes similar to the mice with the effects of decreased hepatic FNDC4 levels (AAVshFNDC4 mice)." (PMID 34016966, 2021).
lung adenocarcinoma (2 papers, 2022 to 2024). A carcinoma that arises from the lung and is characterized by the presence of malignant glandular epithelial cells. "Conversely, upregulated FNDC1, FNDC4, FNDC5, and FNDC6 were associated with worse survival in patients with lung adenocarcinoma." (PMID 36626432, 2022).
prediabetes (2 papers, 2021 to 2022). "The reduction of liver FNDC4 mRNA corresponded with sFNDC4-circulating levels, which subsequently resulted in prediabetes in mice." (PMID 36726994, 2022). "We found that the liver primarily controlled the circulating levels of soluble FNDC4 (sFNDC4) and lowering of the hepatokine FNDC4 led to prediabetes in mice." (PMID 34016966, 2021).
Alcohol use disorder (1 paper, 2026). "Large-cohort GWAS for alcohol use disorder (AUD) drug treatment outcomes and AUD risk have repeatedly identified genetic loci that are splicing quantitative trait loci for the fibronectin III domain containing 4 (FNDC4) gene in the brain." (PMID 41505223, 2026).
Alzheimer disease (1 paper, 2021). A progressive, neurodegenerative disease characterized by loss of function and death of nerve cells in several areas of the brain leading to loss of cognitive function such as memory and language. "Through KEGG pathway analysis, it was confirmed that FNDC4 may be related to amyotrophic lateral sclerosis, Alzheimer's disease, Huntington's disease, Parkinson's disease, non‐alcoholic fatty liver and cancer pathways and mainly affects the PI3K/Akt signalling pathway (PRIDE database:PXD025623)." (PMID 34418326, 2021).
colon cancer (1 paper, 2021). "Upregulation of FOSL2 at 2p22 is associated with colon cancer, and increased levels of FNDC4 transcripts are associated with increased inflammation in mouse models and in IBD patients." (PMID 34178034, 2021).
Crohn disease (1 paper, 2016). A gastrointestinal disorder characterized by chronic inflammation involving all layers of the intestinal wall, noncaseating granulomas affecting the intestinal wall and regional lymph nodes, and transmural fibrosis. "Intestinal biopsies obtained during ileocolonoscopy from 52 IBD patients (21 with Crohn's disease, 29 with ulcerative colitis and 2 with unclassified IBD) and 19 controls were analysed for FNDC4 and FNDC5 expression using quantitative reverse transcription–PCR (RT–qPCR)." (PMID 27066907, 2016).
ductal breast carcinoma (1 paper, 2022). "It was found that the level of FNDC4 expression in IDC and mixed lobular and ductal breast carcinoma was low, and this was also found in databases such as TCGA." (PMID 36626432, 2022).
endometriosis (1 paper, 2025). The growth of functional endometrial tissue in anatomic sites outside the uterine body. "The role of “hubs” in these endometriosis-significant interactions was performed by proteins such as FNDC4 (participates in 9 pair interactions), NRBP1 and ZNF512 (7 pair interactions each), C2orf16, GPN1, and KRTCAP3 (6 pair interactions each)." (PMID 41373783, 2025).
Hypertension (1 paper, 2024). The presence of chronic increased pressure in the systemic arterial system. "Finally, sotalol may manage hypertension through upregulating the expression of FNDC4, an anti-inflammatory factor." (PMID 39149283, 2024). "Utilizing our computational repurposing approach, we propose three mechanisms by which sotalol may moderate hypertension (a condition characterized by increased arterial blood pressure) through potassium channel activity, ADRB1 and FNDC4." (PMID 39149283, 2024).
Impaired glucose tolerance (1 paper, 2021). An abnormal resistance to glucose, i.e., a reduction in the ability to maintain glucose levels in the blood stream within normal limits following oral or intravenous administration of glucose. "In addition, liver FNDC4 mRNA levels decreased in obese humans with impaired glucose tolerance and impaired insulin tolerance (IGT/IIT) and in obese subjects with clinically diagnosed T2D compared to normoglycemic, non-diabetic (ND) lean controls." (PMID 34016966, 2021).
lung carcinoma (1 paper, 2025). "T-cell exhaustion and elevated fibronectin type III domain-containing protein 4 (FNDC4) expression are independently associated with poor prognosis in lung cancer." (PMID 40904557, 2025).
osteoporosis (1 paper, 2018). A condition of reduced bone mass, with decreased cortical thickness and a decrease in the number and size of the trabeculae of cancellous bone (but normal chemical composition), resulting in increased fracture incidence. "FNDC4 could be a novel regulator of osteoclast formation and has therapeutic potential for osteoporosis." (PMID 29977911, 2018).
ovarian serous adenocarcinoma (1 paper, 2022). An adenocarcinoma that arises from the ovary and is characterized by the presence of malignant epithelial cells that, in well differentiated tumors, resemble the epithelium of the fallopian tube or, in poorly differentiated tumors, show anaplastic features and marked nuclear atypia. "Meanwhile, the expression levels of FNDC4 and FNDC5 were lower in ovarian serous adenocarcinoma in the Yoshihara dataset." (PMID 36626432, 2022).
pneumonitis (1 paper, 2022). An inflammatory process affecting the lung parenchyma. "Several of these filtered candidates were found to be secreted (C12orf49, COL10A1, FNDC4, ITLN2, MATN3, PDZD2, RS1, SCRG1, and ST6GALNAC5) making them potential candidate biomarkers useful for distinguishing IPF from pneumonitis." (PMID 35628257, 2022).
prostate tumors (1 paper, 2022). "In the Oncomine database, there are only 3 datasets for FNDC3A, FNDC4, and FNDC5, which indicate statistically notable distinctions between prostate tumors and normal tissues." (PMID 36626432, 2022).
rheumatoid arthritis (1 paper, 2024). A chronic, systemic autoimmune disorder characterized by inflammation in the synovial membranes and articular surfaces. "The latest research showed that FNDC4 dramatically reduced the incidence of rheumatoid arthritis (RA), affected the progression of endothelial corneal malnutrition, and also contributed to the onset of male schizophrenia." (PMID 39325938, 2024).
cancer (5 papers, 2021 to 2024). A tumor composed of atypical neoplastic, often pleomorphic cells that invade other tissues. "Previous studies have demonstrated that overexpression of CRABP2 and FNDC4 can enhance cell invasion and metastasis in various cancers." (PMID 39768218, 2024). "Given the roles of CRABP2 and FNDC4 in cancer progression, they are being explored as potential biomarkers or therapeutic targets in various cancers." (PMID 39768218, 2024). "Through KEGG pathway analysis, we confirmed that FNDC4 is related to cancer pathways and mainly affects the PI3K/Akt signalling pathway." (PMID 34418326, 2021). "Importantly, suppression of CRABP2 or FNDC4 reduced cancer invasion, even in the presence of GRPR overexpression, suggesting that these genes play a critical role in LUAD metastasis." (PMID 39768218, 2024). "Previous studies on FNDC4 have mainly focused on its functions in reducing the inflammatory response and inhibiting osteoclast formation and bone resorption, while there are still few reports on its potential function in the growth and metastasis of cancer cells." (PMID 38021165, 2023). "In addition, FNDC4 was negatively correlated with AFP, a tumor marker of HCC, and other cancer-related genes such as AHSA1, GDF1, GPC3 and MDK." (PMID 38021165, 2023). "Oncomine revealed that the mRNA expression levels of FNDC1, FNDC3A, and FNDC3B were higher in most malignancies than in normal tissues, but the mRNA expression levels of FNDC4, FNDC5, FNDC7, and FNDC8 were downregulated in most cancers when compared with normal tissues." (PMID 36626432, 2022).
tumor (5 papers, 2021 to 2024). "In addition, we found that FNDC4 was associated with the abundance of several tumor-infiltrating lymphocytes and the expression of chemokines and immunostimulators, and FNDC4 was enriched in response to transforming growth factor β." (PMID 38021165, 2023). "In addition, the group with high FNDC4 expression was significantly associated with shorter overall survival (p = 0.002) and was more likely to have tumour recurrence (p = 0.0277)." (PMID 34418326, 2021). "The expression level of FNDC4 varies in different tumors, indicating a certain relationship with tumor prognosis." (PMID 39325938, 2024). "We found that FNDC4 was inversely correlated with AHSA1 and GDF1, two novelly identified genes that were shown to be positively associated with tumor progression in HCC." (PMID 38021165, 2023). "At the same time, we also speculated that overexpressed FNDC4 regulates tumor progression and affects tumor proliferation by affecting the S phase of tumor cells." (PMID 36056336, 2022). "Moreover, we found that FNDC4 overexpression in U87 and U251 cells resulted in increased proliferation and affected the S phase of tumor cells, whereas cell apoptosis remained unchanged." (PMID 36056336, 2022). "Based on these findings, we speculated that FNDC4 may play an important regulatory role in tumor status and interactions with the TIM." (PMID 36056336, 2022). "Furthermore, FNDC4 promotes tumor migration and invasion in hepatocellular carcinoma via the phosphoinositide 3-kinase (PI3K)/Akt signaling pathway." (PMID 36056336, 2022). "Currently, there are relatively few research reports on FNDC4 in tumours." (PMID 34418326, 2021). "In addition, the results also indicated enhanced apoptosis ratio and decreased proliferation ability in HepG2 cells overexpressing FNDC4, which suggested that the decreased expression of FNDC4 may have a favorable effect on tumor growth." (PMID 38021165, 2023). "Secondly, the precise mechanism through which FNDC4 exerts its effects on different tumor cells has not yet been fully elucidated." (PMID 39325938, 2024). "However, since the correlation between AFP, GPC3, MDK, DKK1 and FNDC4 is not high, the sensitivity of FNDC4 as a tumor marker still needs further study." (PMID 38021165, 2023). "Moreover, we showed that FNDC4 overexpression promoted tumor proliferation and affected the S phase of tumor cells in the absence of significant changes in cell apoptosis progression." (PMID 36056336, 2022).
inflammation (3 papers, 2016 to 2020). Aberrant reaction of the microcirculation characterized by movement of fluid and leukocytes from the blood into extravascular tissues. "To investigate whether the inflammation-induced regulation of Fndc4 in mice translates to humans, we analysed FNDC4 and FNDC5 expression in patients with IBD and controls without intestinal inflammation." (PMID 27066907, 2016).
FNDC4 also shares sentences with these, for which no sentence is quoted: hyperlipidemia (3 papers); Hyperglycemia (2); amyotrophic lateral sclerosis (1); and Central Nervous System cancer (1); atherosclerosis (1); cardiovascular diseases (1); cervical cancer (1); dyslipidemia (1); gastric cancer (1); Glucose intolerance (1); Huntington disease (1); Hyperinsulinemia (1); immune disorders (1); liver fibrosis (1); melanoma (1); nephritis (1); non-alcoholic fatty liver (1); ovarian carcinoma (1); Parkinson disease (1); preeclampsia (1); type 2 diabetes (1); ulcerative colitis (1).